MAP2K1 (mitogen-activated protein kinase kinase 1)
Diseases named in the same sentence as MAP2K1 in open-access papers (continued):
Sharing a sentence is not in itself a finding about the gene and the disease.
tumor (452 papers, 2002 to 2026). "This is consistent with previous studies on benign and intermediate melanocytic tumours with MAP2K1 mutations, where a tumour with a Class I mutation also had a co-driver HRAS mutation." (PMID 40107205, 2025). "A total of 31 distinct MAP2K1 mutations were identified, with 20 tumours (19.6%) harbouring Class I mutations, 56 tumours (54.9%) having Class II mutations, and 26 tumours (25.5%) having Class III mutations." (PMID 40107205, 2025). "The tumours displayed spitzoid histomorphology in over two-thirds of cases and harboured 31 distinct MAP2K1 mutations: 20 Class I (19.6%), 56 Class II (54.9%), and 26 Class III (25.5%)." (PMID 40107205, 2025). "In contrast, only 10 out of 20 tumours (50.0%) with Class I MAP2K1 mutations and additional MAPK pathway mutations exhibited spitzoid histomorphology." (PMID 40107205, 2025). "In 74 tumours (72.5%), MAP2K1 mutations, all classified as either Class II or III, were the sole identified drivers." (PMID 40107205, 2025). "Among the 76 tumours driven solely by Class II or III MAP2K1 mutations, 59 (77.6%) showed spitzoid histomorphology." (PMID 40107205, 2025). "Future studies should focus on refining diagnostic criteria, exploring therapeutic targets specific to MAP2K1-driven tumours, and assessing the impact of co-occurring mutations on treatment outcomes." (PMID 40107205, 2025). "A cross-tumor prospective trial is needed to evaluate the efficacy of MEK-inhibitors in MAP2K1-mutated tumors." (PMID 39314226, 2024). "The four reported cases were the first spitzoid neoplasms identified in our practice showing a pathogenic MAP2K1 mutation, indicating a MAP2K1 mutation is a rare genomic driver in these neoplasms." (PMID 33040161, 2021). "75% (3/4) of the tumors harboring MAP2K1 mutation were encapsulated with only one case showing tumor capsule invasion." (PMID 34046359, 2021). "In univariate analyses, three factors, namely MAP2K1/2 mutations, tumour stage (stage 4 vs stage 3), and the presence of lactate dehydrogenase (LDH; 1 vs 0), were found to be associated with immunotherapeutic OS and PFS." (PMID 35069558, 2021). "Taken together, it is plausible that the F129L‐activating mutation in MAP2K1 is an acquired mutation that leads to tumor resistance to ALK‐Is." (PMID 34058070, 2021). "The MAP2K1 mutation yielding a p.Cys121Ser coding shift was the most common in the combined HCLv/HCLc-IGHV4-34 tumour panel, and MAP2K1 mutations associated with predicted constitutive enzymatic activity." (PMID 26871591, 2016). "We have found MAP2K1 (MEK1) as a functional protein in regressor EVs that could activate tumour‐associated macrophages to initiate an interferonγ (IFNγ)‐dependent anti‐tumour immune response." (PMID 39330930, 2024). "A recent retrospective review of the AACR genie, a clinico-genomic database showed that co-occurring MAPK-pathway mutations (e.g., NRAS, NF1) are significantly more likely with class-1 MAP2K1-mutations (82.3%) compared to class-2 (30.9%) and class-3 (10.6%) in any tumor type." (PMID 39314226, 2024). "In co-culture experiments with patient-derived, autologous anti-tumor T cells, pretreatment with MEK inhibitor enhanced cancer cell killing by T cells relative to controls treated with drug alone, except in tumor organoids harboring the MAP2K1 S194P drug addiction variant." (PMID 39424923, 2024). "Additional subclonal hits such as CXCR4 and MAP2K1 mutations could be acquired during tumor progression." (PMID 36797797, 2023). "Our result indicated that hsa_circ_0001013, hsa-miR-485-3p, MAP2K1, and Tgd cells may be associated with tumor metastasis in the development of GC." (PMID 35280778, 2022). "Based on these four cases, we hypothesize that in a part of the spitzoid neoplasms, a mutation in MAP2K1 is the initiating genomic event." (PMID 33040161, 2021). "Hence, MAP2K1/MEK1 mutations were the second most common driver of resistance in this small series that was predominated by tumours with acquired resistance." (PMID 33322618, 2020).
tumor (continued). "Notably, MAP2K1 E102–I103 deletion was frequently observed in pre-invasive samples, which endowed alveolar type II cells with increased growth potential and initiated tumor formation, suggesting that it is a potential driver mutation of LUAD." (PMID 41345544, 2025). "Hence, a combined therapy which involves BRAF and mitogen-activated protein kinase kinase 1 (MAP2K1/MEK) inhibitors may be used to improve patient response in cases where the tumour contains multiple targetable mutations." (PMID 34680938, 2021). "Therefore, we favor that the MAP2K1 change is an acquired mutation that represents tumor evolution." (PMID 32868820, 2020). "The detection of MAP2K1 mutations could inform trials of MEK-inhibitors in these tumours." (PMID 33322618, 2020). "Our research uniquely demonstrates that downregulation of MAP2K1 is a critical mechanism by which MALAT1 inhibition suppresses tumor progression, including proliferation, migration, and EMT processes." (PMID 39319867, 2025). "Our clinical and genomic findings suggest that Class II and III MAP2K1-driven tumours align more closely with conventional WHO pathways of melanomagenesis." (PMID 40107205, 2025). "The significantly higher frequency of NF1, ACVR1, MAP2K1, and AKT1 mutations in EOCRC H/L patient data support the call for expanded investigation into their biological significance in tumor development and treatment response." (PMID 40227607, 2025). "Knockdown of lncRNA MALAT1 significantly reduced tumor volume compared to the control group, while MAP2K1 overexpression produced the opposite effect." (PMID 39319867, 2025). "Our method can not only uncover disease-causing genes with abnormal expression in tumor samples such as CD74, HGF, but it can also identify genes with stable expression yet crucial roles in LUSC, such as BRAF, KDM6A, MAP2K1, and TPR." (PMID 40136480, 2025). "We compared 50 patients with normal liver tissue with 168 stage 1, 84 stage 2, 82 stage 3, and 6 stage 4 LIHC patients: MAP2K1/3 were low expressed in all tumor stages (P < .05)." (PMID 40587753, 2025). "Further features, such as NF1 loss, MAP2K1 mutations, ERBB2 activation, and frequent copy number changes (including CDKN2A/2B deletion and 1p/1q imbalances), add to tumor heterogeneity and evolution." (PMID 41376748, 2025). "Single-cell analysis resolved 23 transcriptionally distinct clusters; proliferative malignant cholangiocytes selectively over-expressed ABCA1 and MAP2K1, indicating tumor-cell specificity." (PMID 41373405, 2025). "We showed that, based on the differential high expression, inhibition of either MAP2K1 or DDR2 reduced tumor growth, and a combination therapy almost completely suppressed tumor growth." (PMID 38554776, 2024). "In order to elucidate the regulatory mechanism of circ_0000069 with the hub genes, we examined the expression of circ_0000069, CCL25, and MAP2K1 in tumor tissues and adjacent non-tumor tissues from 30 paired HCC patients." (PMID 38992592, 2024). "AHR promotes immune evasion and tumor progression, influencing MAP2K1 and PRKACB, which regulate key pathways like MAPK and NF-κB signaling, respectively." (PMID 39835132, 2024). "There are frequent genomic alterations in these neoplasms, especially in the mitogen-activated protein kinase pathway, including BRAF (notably BRAF V600E), MAP2K1, KRAS, and NRAS mutations, and ALK gene translocation." (PMID 38713245, 2024). "A significant increase was observed in single-nucleotide variants in the genes ATM, ATR, BRCA1, LRP1B, MAP2K1, PIK3CG and ZNF217 in addition to BRAF, KRAS, NRAS and EGFR among tumours receiving prior anti-EGFR." (PMID 37569598, 2023). "In a recent study, MAP2K1 alterations were reported in neoplasms with heterogeneous cell morphology, including melanocytic tumors with Spitz cytomorphology, DPN-like architecture with a plexiform pattern, and heavy melanization." (PMID 34205480, 2021).
tumor (continued). "Tumor mutations identified included BRAFV600E in 27 (54%), MAP2K1 in 6 (12%), KRAS in 3 (6%), non-V600 BRAF in 3 (6%), and others." (PMID 33057928, 2021). "Cedric’ study (2020) demonstrated that circRNA-ZFR was highly expressed in HCC tumor tissues and cells, correlated with the poor prognosis of HCC patients, and circRNA-ZFR was also proved to promote tumor cells’ proliferative capacity by targeting MAP2K1." (PMID 35186956, 2021). "Conversely, the subtype-2 tumours expressed significantly higher levels of several proteins, including Stathmin, Mre11 and MAP2K1, than the subtype-1 tumours." (PMID 34506537, 2021). "MiR-16 overexpression reduced cell proliferation in vitro and tumor growth in mice by targeting directly the IGF1R with subsequent inhibition of the Raf1- Mitogen-Activated Protein Kinase Kinase 1/2 (MEK1/2)-ERK1/2 pathway." (PMID 34484116, 2021). "Several reports have identified oncogenic mutations in MAPK kinase 1 (MAP2K1, also called MEK1) as alternative mechanism for MAPK pathway activation in BRAF wild-type tumor in various cancers." (PMID 34046359, 2021). "Genetic analysis of the tumor was performed using a diagnostic biochip for the detection of somatic mutations in the BRAF, NRAS, KIT, GNAQ, GNA11, MAP2K1, and MAP2K2 genes, Sanger sequencing for searching germinal mutations in the CDKN2A gene." (PMID 30782194, 2019). "Analyzing 10,000 tumor exomes, we identify more than 3000 rarely mutated residues in proteins as potentially functional and experimentally validate several in RAC1 and MAP2K1." (PMID 28115009, 2017). "It is significant that a set of the most strongly associated proteins (p <0.01), DFFA, MAP2K1, E2F5, PARP1, predict for longer survival when decreased, which is as would be expected, as these proteins have tumour-promoting characteristics." (PMID 25177240, 2014). "An important question is whether MAP2K1-driven tumours align with conventional WHO melanomagenesis pathways, alongside BRAF, NRAS, and NF1 mutations, or pathway IV (Spitz), alongside kinase gene fusions and HRAS mutations." (PMID 40107205, 2025). "Collectively, lncRNA MALAT1 knockdown impeded tumor growth by reducing MAP2K1 expression." (PMID 39319867, 2025). "Primary cutaneous melanocytic tumours harbouring MAP2K1 mutations without second-hit genomic alterations represent a subclass of neoplasms with poorly understood biological behaviour." (PMID 40107205, 2025). "Our study demonstrates that Class II and Class III MAP2K1 mutations have the potential to initiate aggressive tumour behaviour without concurrent MAPK mutations, as evidenced by patients who developed widespread distant metastases and subsequently died." (PMID 40107205, 2025). "In Patient 6, a class III BRAF p.D594N (kinase-impaired) with additional MAP2K1 activating mutation (requiring RAS activation) was detected in the primary tumor but not in the metastasis." (PMID 39912776, 2025). "Additionally, the tumor weight in the shMALAT1 group was markedly lower than that in the control group, whereas it was higher in the shMALAT1+MAP2K1-OE group." (PMID 39319867, 2025). "Additionally, a nude mouse xenograft model was used to confirm the role of lncRNA MALAT1/MAP2K1 in tumor growth." (PMID 39319867, 2025). "Notably, overexpression of MAP2K1 counteracted the anti-tumor effects induced by MALAT1 suppression in HSCC, promoting FaDu cell proliferation and invasion while diminishing apoptosis and hindering cell cycle arrest." (PMID 39319867, 2025). "Similarly, we identify mutations in both tumor-suppressor genes, e.g., ABL1, JAK2, MAP2K1, and KIT, from poor responders in CML, suggesting that these are two of the key mechanisms by which tumor cells evolve to acquire drug resistance." (PMID 38459554, 2024).
tumor (continued). "In the TCGA-HNSC cohort, we found that ACTB, MAP2K1, PARVB, and PDGFA were upregulated in tumour tissues, suggesting that gene expression may be associated with tumourigenesis." (PMID 37691922, 2023). "Pim inhibitor therapy (Smi-4a) could also synergize with mitogen-activated protein kinase kinase 1/2 (MEK1/2) inhibitor (U0126) in reducing tumor burden in T-ALL and B-ALL engrafted mouse tumors." (PMID 36694243, 2023). "Copper is also an essential cofactor of various metalloproteins known to be closely correlated with tumor growth and metastatic invasion (Mitogen-Activated Protein Kinase Kinase 1 (MAP2K1), lysyl oxidase (LOX) and lysyl oxidase-like, (LOXL), Secreted Protein Acidic and Cysteine Rich (SPARC)...)." (PMID 35456648, 2022). "Our omics analysis of clinical data from cohorts of NSCLC revealed that dysregulation of EGFR/MAP2K1/MTOR/YAP1 signaling pathways are associated with disease progression, anticancer drug resistance, tumor immune infiltration, immune-invasive phenotypes and worse prognosis of the cohorts." (PMID 35655775, 2022). "It is of note that the ICH tumor also carried a mutant MAP2K1." (PMID 32372223, 2020). "Genetic analysis of tumor tissue was performed using a diagnostic biochip (EIMB RAS, Russia) for the detection of most common somatic mutations in the BRAF, NRAS, KIT, GNAQ, GNA11, MAP2K1, and MAP2K2 genes." (PMID 30782194, 2019). "In tumor cells, inhibition of the mitogen-activated protein kinase kinase MEK1 (also known as MAP2K1) can dramatically arrest growth, and high expression of the immunosupressive programmed cell death protein 1 ligand 1 (PD-L1) has been associated with resistance." (PMID 27887656, 2016). "Bertotti et al35 recently carried out exome sequence and copy number analyses of both patient‐derived xenografts and patient tumours, to investigate the effects of mutations in ERBB2, EGFR, FGFR1, PDGFRA and MAP2K1 in relation to resistance to anti‐EGFR therapies." (PMID 26690310, 2016). "Apart from MAP2K1, other gene mutations were far less common in HCLv/HCLc-IGHV4-34 exomes, indicating that the MAP2K1 mutation is dominant and a driver in atypical HCL origins and progression (i.e. in HCLv/HCLc-IGHV4-34 tumours)." (PMID 26871591, 2016). "By examining MAP2K1 mutations more broadly by standard Sanger protocols, the overall frequency of mutations in MAP2K1 was identified as 48% in a panel of HCLv/HCLc-IGHV4-34 tumours (n = 21)." (PMID 26871591, 2016). "Similarly to MAPK3, MAP2K1 (MEK1) mediates FGF-stimulated endothelial-cell proliferation in tumor models." (PMID 22355249, 2012). "None of the tumours with Class III MAP2K1 mutations had co-driver mutations." (PMID 40107205, 2025). "Furthermore, in the multivariable Cox proportional hazards regression model adjusted by tumour stage, LDH, and MAP2K1/2 mutations, these three factors were still significantly associated with OS (HR = 0.24; 95% CI, 0.059–0.99; p = 0.048) and PFS (HR = 0.39; 95% CI, 0.16–0.99; p = 0.048)." (PMID 35069558, 2021). "Previous studies have reported that miR-149-5p functions as a tumor suppressor in HCC by inhibiting the expression of AKT1, MAP2K1, and MTHFR." (PMID 39885395, 2025). "Cu can directly bind to mitogen-activated protein kinase kinase 1 (MEK1) to promote the phosphorylation of ERK1/2 and further activate the downstream c-Jun N-terminal kinase (JNK) to regulate tumor growth." (PMID 41198664, 2025). "Functionally, our findings demonstrate that increased MAP2K1 expression counteracts the inhibitory effects observed upon lncRNA MALAT1 knockdown, thereby promoting malignant biological behaviors and tumor growth in HSCC cells." (PMID 39319867, 2025). "Correlation analysis between the feature genes and immune cell signatures revealed that MAP2K1 and PRKACB are positively correlated with CD4+ T cells and immune score, both of which are crucial for anti-tumor immunity." (PMID 39835132, 2024).
tumor (continued). "BRAFVal600 phosphorylates and activates Mitogen-activated protein kinase kinase 1 (MEK1) and MEK2, which in turn phosphorylate and activate ERK1/2, stimulating the MAPK pathway and ultimately promoting tumor growth." (PMID 38357312, 2024). "Results showed that the regulatory factors CRNDE, EDN1, JUNB, and MAP2K1/2, ZFP36 mainly regulate differentially expressed genes (VEGFA, EGFR, PLAUR) to regulate invasion of cells, invasion of tumor, and microtubule dynamics." (PMID 38711992, 2024). "Copper directly binds to mitogen-activated protein kinase kinase 1 (MEK1), promoting the phosphorylation of ERK1/2 and activating the downstream c-Jun N-terminal kinase (JNK) to regulate tumor growth." (PMID 38693584, 2024). "Previous studies have demonstrated that kinases such as RET, MAP2K1, ALK, and FGF can promote tumor growth via helping tumor cells to evade the immune system by downregulating HLA-I expression." (PMID 38407266, 2024). "In this study, we employ multi-omics approaches based on bulk and single-cell transcriptomic datasets to investigate the role of MAP2K1, mTOR, YAP1 and EGFR in the tumor immune context of tumor microenvironment." (PMID 35655775, 2022). "Simultaneous infection of stromal and tumor cells; Upregulation of Fez1 and Pycard; Downregulation of DLL-4, Angiopoietin 2, PECAM, Tie-1, and FOS EGR2, CREB-5, IL-6, Map2K1, CCL22, TIMD4 and CCL19." (PMID 35640930, 2022). "The mRNA expression of PSMD12 was closely related to MAPK1 and MAP2K1, which indicates that PSMD12 is most likely to regulate tumor progression by the ERK pathway." (PMID 36137220, 2022). "Compared to previous studies, the clinico-pathological characteristics of MAP2K1 mutant CRC cases in our cohort differed with respect to gender distribution, tumor location and tumor stage." (PMID 34046359, 2021). "We found significant associations between tumor mRNA expression of IL2RB and NOTCH1 genes and gender and between tumor mRNA expression of IL2RA and MAP2K1 genes and age." (PMID 33672900, 2021). "Drawing insights into the functions of these genes, several tumor proliferation-related genes (EGFR, NOTCH1, and MAP2K1) and the anti-apoptosis related genes (BCL2L1, XIAP) were detected." (PMID 33637972, 2021). "Several key proteins such as MAP2K1, ITGB4, ITGA6, PTPN6, FMNL1, ANXA1, and MMP9 that modulate cell motility and tumor cell invasion were upregulated in MIBUC." (PMID 32326232, 2020). "Consistently, higher expression in tumor samples for two of the up-regulated genes (MAP2K1 and TRAF4) and lower expression in tumor samples for down-regulated genes (FAS) was observed to evidence their tumor specific regulation." (PMID 29254206, 2017). "SNP array identified copy number alterations in 15q22 (MAP2K1) in 21 tumours (38.9%), with 14 (66.7%) exhibiting stromal fibrosis, compared to only 7 of 33 tumours (21.2%) without gain of 15q22." (PMID 40107205, 2025). "In contrast, MAP2K1 is broadly expressed across cholangiocyte lineages but is most enriched in the malignant and highly proliferative subsets (log2FC: 25.16, padj = 8.29 × 10−139), aligning with MAPK pathway activation in tumor cells." (PMID 41373405, 2025). "One tumour demonstrated a MAP2K1 alteration in the primary that was not replicated in the longitudinal sample." (PMID 39948623, 2025). "Whole exome sequencing (WES) identified a KEAP1/STK11 co-mutation with loss of function for both genes, a MAP2K1 activation, and an ARID2 loss of function, as well as a low tumor mutational burden (TMB) with no actionable mutation (4.4 mut/Mb)." (PMID 39170614, 2024). "The upregulation of key regulatory genes in the MAPK pathway, such as MAP2K1, MAP2K2 and SHC1, in tumour cells positive for the three integrin receptors further supports the involvement of the integrin‐MAPK signalling pathway in the functional maintenance of the C0 subpopulation." (PMID 38279519, 2024).